BDNF (brain derived neurotrophic factor)
Diseases named in the same sentence as BDNF in open-access papers (continued):
Sharing a sentence is not in itself a finding about the gene and the disease.
depression (continued). "Injections of G. lucidum polysaccharides led to a rapid and robust antidepressant-like effect in the chronic social defeat stress model of depression through a mechanism that involved the inhibition of proinflammatory cytokine levels and elevation of BDNF." (PMID 38720779, 2024). "As a critical molecule influencing the hippocampus’s maintenance and remodeling, reduced levels of brain-derived neurotrophic factor (BDNF) in the hippocampus are related to depression." (PMID 39201521, 2024). "As BDNF is also a common marker of depression, we examined BDNF expression levels in the hippocampi of mice." (PMID 39519726, 2024). "Increased levels of proinflammatory cytokines can also induce a chain reaction known as oxido-nitrosative stress, whereby elevated nitrite levels and ROS probably promote depression by inhibiting BDNF expression." (PMID 39061415, 2024). "The findings from both pairwise and network meta-analyses suggest that AERE significantly elevates BDNF levels in patients with depression (MD = 3.36, 95% CrI [1.11–5.64]; SUCRA, 77.28%)." (PMID 40226670, 2024). "In rats, fecal microbiota transplantation had an antidepressant effect in the treatment of depression by increasing, among others, BDNF expression levels and serotonin." (PMID 39275207, 2024). "Collectively, these findings underscore the notable antidepressant‐like role of the LCTH‐dLSSST pathway in depression via BDNF‐TrkB signaling." (PMID 38155473, 2024). "Pertaining to mental health, CRF is directly related to the expression of the molecule brain-derived neurotrophic factor (BDNF); where low levels of this protein are associated with major depression." (PMID 39333320, 2024). "Oleanolic acid produced antidepressant‐like effects in mice exposed to chronic stress, while decreased SGK1 and activated BDNF‐AKT/mTOR signaling in the hippocampus in an animal model of CORT‐induced depression." (PMID 37905694, 2024). "For example, in older women with anxiety/depression, increased DNA methylation of BDNF was found, particularly in BDNF Val66Met heterozygotes." (PMID 39935805, 2024). "There was a tendency for a greater increase in BDNF levels with an increase in the Goldberg depression subscale." (PMID 38396487, 2024). "In an inflammatory mouse model of depression, anxiety-like behavior is comorbid with depressive-like behavior as an indication of BDNF involvement in depressive-like behavior." (PMID 38539677, 2024). "It has been shown that BDNF is intricate in many neurological disorders such as Alzheimer's disease (AD), multiple sclerosis (MS) and depression." (PMID 38752280, 2024). "Future studies will be important in elucidating the role of glutamate within the circuit and in investigating the effects of BDNF overexpression on depression‐like behavior at the circuit level." (PMID 38155473, 2024). "Stress can often precipitate the onset of depression and stress has been shown to decrease BDNF mRNA levels (see for review:)." (PMID 39194496, 2024). "BDNF participates in the pathophysiological process of depression mainly through the induction of intracellular tyrosine residue autophosphorylation and receptor dimerization by binding to TrkB." (PMID 39539631, 2024). "Decreased levels of BDNF protein and mRNA expression have been observed in the brains of individuals suffering from Alzheimer’s and Huntington’s diseases, as well as depression and schizophrenia." (PMID 39682677, 2024). "It was found that the decrease in anxiety and depression behaviors after valsartan treatment in rats exposed to chronic stress was accompanied by an increase in BDNF production." (PMID 39443283, 2024). "FMT from antibiotic-induced depressed mice to normal mice resulted in the development of depression-like behavior, along with significantly reduced levels of norepinephrine, 5-HT, and BDNF in the hippocampus and PFC tissues." (PMID 38983862, 2024).
depression (continued). "Reduced BDNF exacerbates depression-like behaviors - selective BDNF deactivation in the hippocampus resulted in depression-like disorders." (PMID 39717381, 2024). "This meta-analysis systematically evaluated the impact of six distinct exercise interventions—CAE, AERE, RE, yoga, Qigong, and mindfulness—on BDNF levels among adults with depression, assessing their relative therapeutic efficacy." (PMID 40226670, 2024). "Oral administration of GW043 enhances LTP and activates the BDNF‐mTOR pathway, thereby modulating synaptic plasticity and showing significant antidepressant effects in animal models of depression." (PMID 38332552, 2024). "BDNF has been also studied in different neurological-related diseases, such as major depressive disorders, fibromyalgia syndromes and chronic low back pain." (PMID 38362105, 2024). "Serum or plasma levels of BDNF are typically lower in patients with depression, and antidepressant treatments can increase BDNF levels, suggesting its central role in depression pathology." (PMID 39329797, 2024). "Participants were subjected to a battery of neuropsychological tests for anxiety and depression behavior, and the results have been correlated to circulating BDNF." (PMID 39596862, 2024). "In preclinical models of stroke, aerobic exercise improves neurobehavioral symptoms, such as depression, by regulating BDNF expression in both adult and juvenile animals." (PMID 38397427, 2024). "A recent study observed that training exercise improves depressive symptoms in patients with depression by increasing circulating BDNF serum levels." (PMID 37953501, 2024). "The neurotrophic theory of depression stipulates that low levels of BDNF increase vulnerability to stress." (PMID 38720779, 2024). "There is growing evidence that stress targets BDNF, suggesting that the BDNF/TrkB pathway is critical for stress- related depression and anhedonia." (PMID 38796504, 2024). "Altogether, the key findings obtained from this study suggest the potential effect of ZZCD treatment on restricting oxidative stress and neuron injury following depression by upregulating Six3os1 and BDNF expression." (PMID 38818577, 2024). "Neuroplasticity is modulated in individuals with depression, where the ratio of BDNF to pro-BDNF plays a essential role in synaptic plasticity." (PMID 38389919, 2024). "The use of S-Ketamine, an FDA-approved medication for treatment-resistant depression, in rodents following chronic unpredictable stress produces increased brain-derived neurotrophic factor (BDNF) and SIRT1." (PMID 39404407, 2024). "Based on these results, they proposed that when studying the relationship between depression and BDNF, comorbidities and physical conditions." (PMID 39648800, 2024). "A follow-up study in rats with poststroke depression showed that intranasal administration of BDNF-HA2TAT/AAV increased BDNF mRNA and protein levels in the prefrontal cortex, leading to improvements in neurological function after intranasal gene therapy." (PMID 39062095, 2024). "From this observation, the link between butyrate and depression emerged, as BDNF genes in the prefrontal cortex showed increased acetylation induced by butyrate." (PMID 39063542, 2024). "The research was done to better understand the interaction between chronic stress and the BDNF Val66Met variation that results in depression in Chinese healthcare professionals." (PMID 38252222, 2024). "Compelling evidence from our research indicates that both BDNF and antagomir offer promising therapeutic avenues for mitigating depression-like behaviors in mouse models." (PMID 39588356, 2024). "We aimed to investigate the alterations in BDNF expression and global DNA methylation in depression among adolescent girls." (PMID 38542252, 2024). "Subjects with both PD and depression, as well as PD alone, had significantly decreased BDNF levels when compared to healthy controls." (PMID 39712854, 2024).
depression (continued). "Some studies have demonstrated that GR levels are upregulated upon stress elevation by targeting BDNF levels, and the knockdown of GR ameliorates depression like-behavior in mice." (PMID 39574138, 2024). "In the present study, the effects of ALLO treatment on the depression- or anxiety-like behaviors and the BDNF and β-catenin expression in the IL were observed in the estradiol-withdrawal model of PPD." (PMID 38743109, 2024). "Analysis of the GSE84183 dataset indicated low BDNF expression in the hippocampal tissue samples of mice with depression‐like behaviours." (PMID 38818577, 2024). "Esketamine also shows promise in perioperative settings for reducing depression and anxiety, and these effects appear to correlate with increased peripheral biomarkers such as brain-derived neurotrophic factor and serotonin." (PMID 38997425, 2024). "A close relationship between lipotoxicity and anxiety, anhedonia, depression and reduction of BDNF in the brain of animals and humans has also been suggested." (PMID 40255947, 2024). "The pairwise meta-analysis indicated that all exercise interventions significantly elevated BDNF levels in patients with depression, with AERE, RE, and yoga demonstrating the most substantial effects." (PMID 40226670, 2024). "In clinical studies, antipsychotic treatment has been found to promote many forms of neuroplasticity and increases in BDNF expression, and increased serum BDNF has been regarded as a candidate biomarker for the successful treatment of depression." (PMID 39058106, 2024). "Alterations in brain-derived neurotrophic factor (BDNF) expression have been suggested to mediate the influence of environmental factors on the emergence of depression through epigenetic modifications." (PMID 38542252, 2024). "Although the literature presents some inconsistencies, it has been described that BDNF signaling is impaired in rodent models of depression induced by stress, as well as in individuals diagnosed with depression." (PMID 39767653, 2024). "Abnormal oxidative stress and inflammation in patients with depression impair neuroplasticity by inhibiting the expression of BDNF and NGF." (PMID 39114351, 2024). "BDNF, a major member of this family, has garnered the attention of clinicians in depression, making its signaling pathway a focal point in antidepressant research." (PMID 39639753, 2024). "Abundant evidence demonstrates that changes in the expression of BDNF are seen in postmortem brain samples obtained from individuals diagnosed with depression." (PMID 38916735, 2024). "These variables were sex, age, sport, alcohol consumption (AUDIT-C), Goldberg-depression score, cortisol, and BDNF levels." (PMID 38396487, 2024). "Given the crucial functions of BDNF in the diagnosis and response to the treatment of depression, it is important to understand the role it plays when depression is accompanied by anxiety symptoms, as occurs in a great percentage of MDD cases." (PMID 39408702, 2024). "In conclusion, AT1RB has a therapeutic effect on menopause‐induced depression and anxiety‐like behaviors, likely by reducing oxidative stress and increasing BDNF production in the hippocampus." (PMID 39443283, 2024). "The antidepressant effect of antidepressant drugs is chiefly mediated through increasing BDNF signaling in the hippocampus in mice with resistant depression." (PMID 39654365, 2024). "Studies have shown that chronic CORT can induce depression-like behavior in mice and reduce the expression of BDNF in dentate gyrus (DG) neurons of the hippocampus." (PMID 39494347, 2024). "The researchers concluded that SYT4 and BDNF play crucial roles in the development of anhedonia and stress-induced depression." (PMID 38297157, 2024). "This modification correlates with a significant reduction in BDNF expression, which has been documented both in post-mortem brain tissues and in the blood of individuals with depression, including those exhibiting suicidal behaviors." (PMID 39684808, 2024).
depression (continued). "Depression and AD share some common neurobiological mechanisms, including the dysregulation of neurotrophic factors, such as the brain-derived neurotrophic factor (BDNF)." (PMID 38995015, 2024). "Future studies should involve a longitudinal analysis of BDNF expression in depression across adolescence and adulthood in order to understand the pathogenesis and natural course of the disease." (PMID 38542252, 2024). "Patients with major depression show an appreciable reduction in serum levels of BDNF, probably due to a reduction of the protein in the brain." (PMID 39170712, 2024). "Research related to depression suggests that the expression of BDNF, can be altered by exogenous SCFAs." (PMID 38357350, 2024). "Studies have shown that the activity and expression of BDNF play an indispensable role in the pathogenesis of depression." (PMID 38615365, 2024). "Our findings confirm the role of BDNF in the pathophysiology of depression but the correlation of BDNF and suicide is yet to be elucidated." (PMID 39039500, 2024). "Research has found that GAS can improve depression‐like behaviors in rats by upregulating the brain‐derived neurotrophic factor (BDNF) expression in their hippocampal astrocytes." (PMID 37650449, 2024). "Differences in cerebral or peripheral concentrations of BDNF have been observed in various neurodegenerative and psychiatric disorders, such as Alzheimer's disease, major depressive disorder and schizophrenia." (PMID 39105714, 2024). "The role of BDNF in synaptic plasticity has been well-established and BDNF levels have been shown to increase alongside slow-wave activity (SWA) following ketamine therapy for depression specifically in responders." (PMID 39376965, 2024). "The elevated presence of NOx within the context of depression not only leads to a reduction in Nrf2 levels but also hampers the signaling of BDNF." (PMID 38180676, 2024). "BDNF is known for its high concentration in the cortex and hippocampus, where it plays a pivotal role in neurological development and mitigating depression via specific pathways." (PMID 41221079, 2024). "One key NTF is brain-derived neurotrophic factor (BDNF), which plays a critical role in the pathophysiology of depression." (PMID 39329797, 2024). "This innovative approach represents a substantial advancement in neurotherapeutics, enabling the efficient delivery of BDNF directly to neurons within the hippocampus and prefrontal cortex, areas critically affected in depression." (PMID 41221079, 2024). "Underneath this concept, several studies exposed that serum BDNF is reduced in diverse neuropsychiatric diseases such as depression." (PMID 38006577, 2024). "Nonetheless, discrepancies exist, as an inverse relationship between blood and hippocampal BDNF levels was observed in a genetic rat model of depression, raising questions about the universality of these correlations." (PMID 39684808, 2024). "Numerous studies have shown the link between brain-derived neurotrophic factor/tropomyosin kinase receptor B (BDNF/TrkB) pathway activation and the improvement of neurological disorders, such as AD or major depressive disorder." (PMID 39274839, 2024). "Previous research highlights these challenges, suggesting that caution is needed when drawing conclusions about the relationship between peripheral BDNF, depression, and physical health outcomes." (PMID 39596555, 2024). "A cohort study on PD patients illustrated that BDNF serum level was reduced mainly in PD women patients with depression and motor dysfunctions." (PMID 38752280, 2024). "In agreement, Akkermansia muciniphila treatment significantly ameliorated depressive-like behavior in mice and restored abnormal variations in depression-related molecules (corticosterone, dopamine and BDNF)." (PMID 38928361, 2024). "For patients with depression, current evidence generally suggests that a MD in BDNF levels postexercise intervention greater than 0 is associated with improvements in depressive symptoms." (PMID 40226670, 2024).
depression (continued). "In the LPS-induced depression model of rats, the reduced level of the BDNF and the related changes of synaptic plasticity in the hippocampus were observed." (PMID 38337722, 2024). "Still, this does not impose the use of BDNF to test the effectiveness of environmental affordance for physical activity to increase AHN, hippocampal volume, and BDNF release; reduce depression; and improve cognition in adult humans." (PMID 39595896, 2024). "Another study showed that among 225 patients with coronary artery disease, serum BDNF levels were lower in patients with comorbid depressive symptoms, suggesting a correlation between serum BDNF levels and depression in patients with coronary artery disease." (PMID 38707889, 2024). "Treatment with valsartan, an angiotensin II type I receptor blocker, reduced depression and anxiety‐like behavioral disorders and protected oxidative stress and BDNF levels." (PMID 39443283, 2024). "The best outcome proved that BDNF, produced in megakaryocytes and accumulated in platelets, is involved in the pathophysiology of depression by modulating thrombosis." (PMID 39061415, 2024). "Neuronal activity-dependent activation of the BDNF gene in the hippocampus—an area of the brain known to be involved in the pathophysiology of depression—is mediated by decreased methylation of BDNF promoter IV, among other mechanisms." (PMID 38542252, 2024). "First, brain-derived neurotrophic factor (BDNF) is lower in older adults and patients with depression, and a decrease in BDNF is associated with an increased risk of depression." (PMID 39949496, 2024). "Our findings suggest its efficacy in mitigating neuroinflammation in a depression-like mouse model by potentially modulating the BDNF-TrkB axis." (PMID 38835076, 2024). "Secondly, while the study explores the BDNF/TrkB/AKT signaling pathway and its involvement in depression, the exact molecular mechanisms underlying the therapeutic effects of RVG-BDNF-Exos remain to be fully elucidated." (PMID 41221079, 2024). "Regarding the balance between pro‐BDNF and mBDNF, studies on depression have shown that pro‐BDNF plays a detrimental role in mood regulation, whereas the overexpression of mBDNF can mitigate the damage caused by pro‐BDNF." (PMID 39648800, 2024). "Research has linked BDNF to depression, and TCM has been shown to improve BDNF levels in individuals with depression." (PMID 38818577, 2024). "Decreased methylation in the BDNF exon IV promoter should be considered as one of the possible biomarkers of a depression state among adolescent girls." (PMID 38542252, 2024). "This was achieved by boosting the production of BDNF and improving hippocampus neurogenesis of a depression rat model." (PMID 39040602, 2024). "With regard to the relationship between BDNF and depressive disorders, there is evidence that expression and activity of BDNF in the hippocampus are decreased in response to stress and increased by antidepressant treatment." (PMID 38169018, 2024). "BDNF plays a crucial role in neuronal survival and synaptic potentiation, and its involvement in the development of depressive disorders and response to antidepressant treatments has been well-recognised." (PMID 38337395, 2024). "It is well established that there is an interplay between BDNF and depressive disorder, especially as a good classifier of MDD diagnosis." (PMID 39408702, 2024). "Our research aims to evaluate the degree of expression of brain neurotrophic factor (BDNF) in brain areas involved in depressive disorder in suicidal subjects." (PMID 39170712, 2024). "One of the most significant biological findings in depression disorders is the decline in peripheral (plasma or serum) BDNF levels." (PMID 39902245, 2024). "In this study, we aimed to investigate the role of the cAMP/CREB/BDNF signaling pathway in Sig-1R knockout-induced depression-like behaviors." (PMID 37089558, 2023).